RNU6-188P (RNA, U6 small nuclear 188, pseudogene)
Gene: Small nuclear RNA gene on chromosome 15 (42,427,591 to 42,427,697, reverse strand). Ensembl gene ENSG00000201077.
Homologues: Orthologues: chimpanzee U6 (99% identical). Paralogues in human: RNU6-1289P (92% identical), RNU6-15P (92% identical), RNU6-1145P (91% identical), RNU6-1316P (91% identical), RNU6-1 (90% identical), RNU6-1013P (90% identical), RNU6-1060P (90% identical), RNU6-116P (90% identical), RNU6-1175P (90% identical), RNU6-11P (90% identical), RNU6-19P (90% identical), RNU6-2 (90% identical), and 1288 more.